LINC00601 (long independently transcribed non-coding RNA 601)
Gene: Long non-coding RNA gene on chromosome 10 (126,412,059 to 126,424,917, reverse strand). Ensembl gene ENSG00000235180.
Diseases named in the same sentence as LINC00601 in open-access papers:
LINC00601 is named in the same sentence as 3 diseases in open-access papers, as found by Europe PMC text mining. Sharing a sentence is not in itself a finding about the gene and the disease. The quoted sentences say what the papers report.
hepatocellular carcinoma (1 paper, 2023). A malignant tumor that arises from hepatocytes. "LINC00601 was found to be upregulated in hepatocellular carcinoma and promoted the development of the disease through the activation of the MAPK signaling pathway." (PMID 37812189, 2023).
LINC00601 also shares sentences with these, for which no sentence is quoted: cancer (1 paper); glioma (1).